SLC7A10 (solute carrier family 7 member 10)
Description:
Associates with SLC3A2/4F2hc to form a functional heterodimeric complex that translocates small neutral L- and D-amino acids across the plasma membrane. Preferentially mediates exchange transport, but can also operate via facilitated diffusion (By similarity). Acts as a major transporter for glycine, L- and D-serine in the central nervous system. At the spinal cord and brainstem regulates glycine metabolism and glycinergic inhibitory neurotransmission by providing for glycine de novo synthesis from L-serine and glycine recycling from astrocytes to glycinergic motor neurons (By similarity). At Schaffer collateral-CA1 synapses mediates D-serine and glycine release that modulates post-synaptic activation of NMDA receptors and excitatory glutamatergic transmission (By similarity). May regulate D-serine release from mesenchymal progenitors located in developing subcutaneous adipose tissue, favoring white adipocyte over thermogenic beige adipocyte lineage commitment (By similarity).
Synonyms: Asc-1; ASC1; HASC-1
Tractability: Small molecule: a structure with a bound ligand is known. Antibody: its Gene Ontology location is reachable by antibodies, with high confidence; UniProt places it where antibodies can reach, with medium confidence; UniProt predicts a signal peptide or a membrane-spanning region.
Gene: Protein-coding gene on chromosome 19 (33,208,657 to 33,225,850, reverse strand). Ensembl gene ENSG00000130876.
Subcellular location: Cell membrane
Subcellular location (Human Protein Atlas): Nucleoli; Nucleoplasm
Pathways (Reactome):
Hemostasis: Basigin interactions
Transport of small molecules: Amino acid transport across the plasma membrane
Gene Ontology:
Molecular function: neutral L-amino acid transmembrane transporter activity; protein binding; L-amino acid transmembrane transporter activity; L-serine transmembrane transporter activity; transmembrane transporter activity
Biological process: neutral amino acid transport; amino acid import across plasma membrane; amino acid transport; D-alanine transmembrane transport; D-serine transmembrane transport; glycine transport; L-alpha-amino acid transmembrane transport; L-serine transport; negative regulation of brown fat cell differentiation; positive regulation of synaptic transmission, glycinergic; transmembrane transport
Cellular component: membrane; plasma membrane; transmembrane transporter complex
Genetic constraint (gnomAD): Loss-of-function variants: 30 observed, 52.64 expected, observed/expected ratio (o/e) 0.57, 90% interval 0.43 to 0.77. The upper end of that interval is the gene's LOEUF score, 0.77, which puts it in group 3 of 6, group 1 being the genes least tolerant of losing a copy. Missense variants: 581 observed, 692 expected, observed/expected ratio (o/e) 0.84, 90% interval 0.78 to 0.9. Synonymous variants: 316 observed, 308.41 expected, observed/expected ratio (o/e) 1.02, 90% interval 0.93 to 1.12.
Homologues: Orthologues: chimpanzee SLC7A10 (98% identical), dog SLC7A10 (93% identical), pig SLC7A10 (93% identical), mouse Slc7a10 (93% identical), rat Slc7a10 (93% identical), guinea pig SLC7A10 (93% identical), rabbit SLC7A10 (86% identical), tropical clawed frog slc7a10 (78% identical), zebrafish slc7a10b (70% identical), zebrafish slc7a10a (69% identical), macaque SLC7A10 (65% identical), Drosophila melanogaster mnd (43% identical), and 12 more. Paralogues in human: SLC7A8 (63% identical), SLC7A5 (45% identical), SLC7A6 (42% identical), SLC7A7 (41% identical), SLC7A11 (40% identical), SLC7A9 (38% identical), SLC7A13 (27% identical), SLC7A3 (22% identical), SLC7A1 (22% identical), SLC7A2 (22% identical), SLC7A4 (21% identical), SLC7A14 (20% identical).
Diseases named in the same sentence as SLC7A10 in open-access papers:
SLC7A10 is named in the same sentence as 24 diseases in open-access papers, as found by Europe PMC text mining. Sharing a sentence is not in itself a finding about the gene and the disease. The quoted sentences say what the papers report.
hyperekplexia (3 papers, 2016 to 2025). "To assess the possible role of Asc-1 in startle disease, we screened genomic DNA from 51 unresolved hyperekplexia patients for variants in all 11 exons including flanking intronic sequences of the human gene (SLC7A10)." (PMID 37903619, 2023). "We conclude that Slc7a10-null mice represent a novel disease model for hyperekplexia, and reveal an astrocytic origin for the phenotype in addition to presently known dysfunction of pre- and post-synaptic elements of glycinergic inhibitory neurons." (PMID 27759100, 2016). "Our findings highlight the possibility that mutations in human SLC7A10 or autoantibodies against human SLC7A10 could underlie a subset of the remaining gene-negative hyperekplexia families or auto-antibody negative individuals with stiff person syndrome." (PMID 27759100, 2016).
Insulin resistance (3 papers, 2021 to 2024). Increased resistance towards insulin, that is, diminished effectiveness of insulin in reducing blood glucose levels. "Further research into SLC7A10 functions in specific adipocyte subtypes may lead to new precision therapeutics for mitigating the risk of insulin resistance and type 2 diabetes." (PMID 36172277, 2022). "In humans, lower expression of the related transporter SLC7A10/ASC-1 in adipose tissue is associated with increased visceral fat, insulin resistance, and adipocyte hypertrophy." (PMID 38678254, 2024). "In the present review we focus on the HAT SLC7A10, which has a particularly high expression in adipocytes and emerged as an important player in metabolic diseases related to obesity, insulin resistance and type 2 diabetes." (PMID 36172277, 2022). "In human cohorts, adipose SLC7A10 mRNA shows strong inverse correlations with insulin resistance, adipocyte size and components of the metabolic syndrome, strong heritability, and an association with type 2 diabetes risk alleles." (PMID 36172277, 2022). "Taken together, these correlative data point to SLC7A10 as an important modulator of insulin resistance and metabolic health via white adipocytes." (PMID 36172277, 2022). "Decreased subcutaneous as well as visceral adipose expression of SLC7A10 mRNA in insulin resistance was confirmed by directly comparing BMI-matched people with obesity who were either insulin resistant or insulin sensitive determined by hyperinsulinemic euglycemic clamp." (PMID 36172277, 2022). "Expression of SLC7A10 in human WAT inversely correlates with visceral obesity and insulin resistance." (PMID 34832860, 2021).
startle disease (2 papers, 2023 to 2025). "Our data provide evidence that in humans SLC7A10 is a rare gene associated with human startle disease." (PMID 37903619, 2023). "Thus, our data suggest that SLC7A10 may represent a rare but novel gene associated with human startle disease and developmental delay." (PMID 37903619, 2023). "Recently, murine studies suggested the solute carrier 7 subfamily 10 (SLC7A10) as candidate gene for human startle disease." (PMID 37903619, 2023). "From murine studies, SLC7A10 (Asc-1) has been recently suggested as a possible additional candidate gene, since Slc7a10 KO mice suffer from startle disease-like symptoms including increased tremor, hind-leg clasping and significantly enhanced righting time." (PMID 37903619, 2023). "Recently, studies on solute carrier 7 subfamily 10 (SLC7A10; Asc-1, alanine-serine-cysteine transporter) knock-out (KO) mice displaying a startle disease-like phenotype hypothesized that this transporter might represent a novel candidate for human startle disease." (PMID 37903619, 2023).
Ataxia (1 paper, 2020). Ataxia refers to impaired coordination of voluntary muscle movement. "In line with this, the phenotype of Slc7a10 KO mice (tremors, ataxia, rigidity, seizure-like events) reflects impaired glycinergic inhibitory transmission." (PMID 33633558, 2020).
colon cancer (1 paper, 2008). "The solute carrier SLC7A10 (changed transport, BP), an inflammatory and apoptosis modulator, increased both in MG-thymoma and in colon cancer, with higher thymus than colon expression." (PMID 18545673, 2008).
developmental delay (1 paper, 2023). "In conclusion, this is the first description of a pathogenic variant in SLC7A10 encoding Asc-1, highlighting the importance of this gene in human startle disease associated with developmental delay." (PMID 37903619, 2023).
head and neck cancer (1 paper, 2021). A primary or metastatic malignant neoplasm affecting the head and neck. "SLC3A2/CD98hc and two L-type amino acid transport binding partners, LAT1 and ascAT1 (derived from SLC7A5 and SLC7A10, respectively), were analyzed independently as prognostic markers in bladder, breast, cervical, lung, renal and head and neck cancers." (PMID 34112739, 2021).
sarcoma (1 paper, 2017). A usually aggressive malignant neoplasm of the soft tissue or bone. "RGS4 and SLC7A10 are two important genes directly associated with sarcoma in previous reports." (PMID 28404969, 2017).
type 2 diabetes (1 paper, 2022). "This latter analysis was motivated by reduced subcutaneous adipose SLC7A10 expression in carriers of risk alleles in the type 2 diabetes-associated locus near the KLF14 gene." (PMID 36172277, 2022).
cancer (3 papers, 2024 to 2025). A tumor composed of atypical neoplastic, often pleomorphic cells that invade other tissues. "Data from the human Cancer Cell Line Encyclopedia (CCLE) demonstrated differential expression of these genes across cell lines, with high expression of PHGDH, PSAT1, SLC1A5 and SLC38A2, and low expression of SLC38A4 and SLC7A10." (PMID 40660426, 2025).
metabolic disease (2 papers, 2022 to 2023). A congenital disorder (due to inherited enzyme abnormality) or acquired (due to failure of a metabolically important organ) disorder resulting from an abnormal metabolic process. "An earlier study had also found inverse correlations between SLC7A10 mRNA expression in subcutaneous adipose tissue and risk factors for metabolic disease (e.g., body-mass index (BMI), fasting glucose, insulin and triacylglycerols)." (PMID 36172277, 2022). "In good agreement, a positive correlation between the adipose tissue SLC7A10 expression and circulating levels of adiponectin has been reported; whereas a negative correlation between SLC7A10 mRNA levels in subcutaneous adipose tissue and risk factors for metabolic diseases has been found." (PMID 38203703, 2023).
tumour (1 paper, 2025). "While the exact transporters involved in serine uptake within tumours remain incompletely defined, members of the solute carrier (SLC) superfamily, such as SLC1A4 (ASCT1), SLC1A5 (ASCT2), SLC7A10, SLC38A2, SLC38A4 and SLC38A5, have been implicated." (PMID 40660426, 2025).
SLC7A10 also shares sentences with these, for which no sentence is quoted: Obesity (2 papers); asthma (1); carcinosarcoma (1); infarction (1); infection (1); metabolic syndrome (1); neurological disorder (1); schizophrenia (1); stiff-person syndrome (1); thymoma (1); Tremor (1); type 1 diabetes (1).